CXCR4 (C-X-C motif chemokine receptor 4)
Diseases named in the same sentence as CXCR4 in open-access papers (continued):
Sharing a sentence is not in itself a finding about the gene and the disease.
liver fibrosis (35 papers, 2012 to 2025). "CXCL12/CXCR4 interactions are involved in immune cell migration and have been associated with liver fibrosis and cirrhosis progression." (PMID 41223189, 2025). "In conclusion, our study reveals that ALB inhibits inflammation and improves liver fibrosis by targeting the CXCL12/CXCR4 axis in CCl4-induced mice." (PMID 40371331, 2025). "AMD3100 can cut off the migration of inflammatory cells to the liver to impede the development of inflammation and inhibit the CXCL12/CXCR4 biological axis in liver fibrosis to protect against the activation of HSCs." (PMID 40002899, 2025). "The research results on the mechanism of action indicated thatthe combination therapysignificantly downregulate the expression levels of key proteins CXCL12 and CXCR4 in a mouse model of liver fibrosis." (PMID 40371331, 2025). "In this study, we found that ALB effectively mitigates liver fibrosis by modulating the CXCL12/CXCR4 axis, thereby inhibiting the expression of profibrotic markers and reducing inflammatory responses." (PMID 40371331, 2025). "The CXCL12/CXCR4 (a CXCL12 receptor) axis modulates liver fibrosis by promoting the activation and the proliferation of the HSCs." (PMID 38360740, 2024). "For example, in an acute liver injury and early chronic liver fibrosis model, mice treated with a CXCR4 antagonist, AMD3100, expressed higher hepatic α-SMA and showed increased hepatic collagen content and fibrosis over untreated controls." (PMID 35336043, 2022). "This study characterized the effect of nanoparticles on miR-155 and CXCR4 expression as well as therapeutic outcomes in a model of hepatic fibrosis during AALD." (PMID 35336043, 2022). "This suggests that the impact of ACKR3 agonism is rather important in the early stages, while CXCR4 antagonism becomes more important in the chronic phase of liver fibrosis." (PMID 35562519, 2022). "CXCR4 promotes the activation and differentiation of HSCs in liver fibrosis through MAPK activation." (PMID 35336043, 2022). "The inhibition of the CXCR4 axis in activated HSCs has been previously used successfully in the treatment of liver fibrosis." (PMID 35336043, 2022). "CXCL12/CXCR4 is also known to activate the ERK1/2 cascade to induce the proliferation of HSCs in liver fibrosis." (PMID 35336043, 2022). "CXCR4 HIV also regulates the progression of liver fibrosis by inducing reactive oxygen species (ROS) production in HSCs and further promoting the expression of fibrogenesis-related genes." (PMID 34386499, 2021). "Here, the expression levels of CXCL12 and CXCR4 are significantly elevated in liver fibrosis and cirrhosis." (PMID 34386499, 2021). "In mice with CCl4-induced liver fibrosis, treatment with Sorafenib/Selumetinib-loaded CXCR4-targeted NPs significantly suppressed hepatic fibrosis progression and further prevented fibrosis and liver metastasis." (PMID 34207175, 2021). "In recent years, with the in-depth study of the mechanism of liver fibrosis, it has been found that CXCR4 and its ligand play a critical role in the pathogenesis of liver fibrosis via the activation and recruitment of various cells." (PMID 34386499, 2021). "CXCR4 antagonist AMD 3100 octahydrochloride hydrate grafted nanoparticles have been shown to inhibit the progression of CCL-4 induced liver fibrosis in mice." (PMID 34064375, 2021). "In vitro and in vivo studies have found that the inhibition of the CXCL12/CXCR4 biological axis in liver fibrosis can protect against the activation and migration of HSCs, and thus attenuates liver fibrosis." (PMID 34386499, 2021). "During chronic liver injury, LSECs persistently express fibroblast growth factor receptor 1 (FGFR1), supporting CXCR4-driven fibrotic angiocrine responses and promote liver fibrosis." (PMID 34064375, 2021). "CXCR4 is a chemokine receptor induced in HSCs by various cellular stresses during the progression of liver fibrosis." (PMID 34207175, 2021).
liver fibrosis (continued). "Currently, several studies have dissected the role of CXCR4 signaling pathway in HSCs and explored therapeutic interventions targeting this pathway in liver fibrosis." (PMID 34386499, 2021). "Taken together, CXCR4 and its ligand are functionally and mechanistically involved in the progression of liver fibrosis." (PMID 34386499, 2021). "In chronic injury, SDF-1 receptor expression switched from the pro-regenerative C-X-C chemokine receptor type 7 (CXCR7) to the pro-fibrotic CXCR4, thereby initiating liver fibrosis." (PMID 30483508, 2018). "We also found slight increase in COL3A1 and CXCR4 both of which play important roles in hepatic fibrosis." (PMID 30024933, 2018). "CXCL12 activates CXC chemokine receptor 4 (CXCR4) resulting in liver fibrosis, tumor growth, and HCC metastasis." (PMID 30034633, 2018). "Among these SHP regulated genes the chemokine CXCL12, together with its primary receptor CXCR4, play a major role during the progression of liver fibrosis by promoting hepatic stellate cell activation and contraction." (PMID 28117422, 2017). "Taken together, our results showed little evidence for a key pathological role of signaling via the CXCL12/CXCR4 axis in either the BLM-induced PF model or the CCl4-induced hepatic fibrosis model." (PMID 26998906, 2016). "On other hand, HIV can infect and/or activate liver cells via co-receptor CCR5 and CXCR4 to accelerate HCV-induced hepatic fibrosis." (PMID 25528160, 2014). "We then investigated the influence of HIV tropism on liver fibrosis by assessing the prevalence of CXCR4-using viruses in two groups of HCV–HIV co-infected patients: one with mild fibrosis (score ≤F2) and the other with severe fibrosis (score >F2)." (PMID 23226258, 2012). "Moreover, CXCL12/CXCR4 also participates in the occurrence of liver fibrosis by promoting the activation and proliferation of hepatic stellate cells." (PMID 40002899, 2025). "Previous studies have demonstrated that chemokine receptor CXCR4 and its ligand in liver disease are very important, playing a key role in multiple liver diseases such as hepatitis, liver injury and regeneration, liver fibrosis, and cirrhosis, as well as in HCC." (PMID 40002899, 2025). "In conclusion, in the CCl4 rat model, there was a substantial correlation between the changes in fibrosis area percentage and the changes in CD34+, SDF-1α, and CXCR4 during the process of liver fibrosis treatment and also during the spontaneous recovery period." (PMID 37730560, 2023). "The therapeutic role of CXCR4 inhibition in liver fibrosis deserves further investigation." (PMID 35336043, 2022). "Interestingly, studies have shown that CXCR4 expression can be induced in activated HSCs during the progression of liver fibrosis." (PMID 34386499, 2021). "Thus, it is necessary to adopt more cell types, combined with targeted delivery or specific strategies to modulate the CXCL12/CXCR4 signaling to target this pathway in liver fibrosis." (PMID 34386499, 2021). "During liver fibrosis, CXCR4 pathway appears to be important for recruiting different cells to the injured liver, which may partly explain contradictory results of this pathway in the process of fibrosis and repair." (PMID 34386499, 2021). "Therefore, specifically targeting CXCR4 for the treatment of liver fibrosis has become a focus of research." (PMID 34386499, 2021). "Given the critical role of HSCs activation in the progression of liver fibrosis, these studies suggest that specific targeting of CXCR4 and its ligand may be beneficial in liver fibrosis." (PMID 34386499, 2021). "Together, these findings indicate that inhibition of CXCR4 has limited impact on hepatic fibrosis." (PMID 26998906, 2016). "Furthermore, following liver injury, increased CXCR7, another CXCL12 receptor, stimulates regeneration, but suppression of CXCR7 function stimulates CXCR4 and induces liver fibrosis instead of regeneration." (PMID 25765541, 2015).
liver fibrosis (continued). "Therefore, the CXCR4 pathway contributes to liver fibrosis, but the CCR5 pathway has also been demonstrated to play a role in mouse models of liver fibrosis." (PMID 23226258, 2012). "Therefore, blocking the CXCR4 signaling pathway through AMD3100 in hepatic stellate cells may directly inhibit the progression of liver fibrosis." (PMID 40002899, 2025). "Furthermore, the study found that AS-IV may further exert its anti-HSC activation and anti-liver fibrosis effects through by regulating the C-X-C motif chemokine ligand 12 (CXCL12)/C-X-C chemokine receptor type 4 (CXCR4) signaling axis." (PMID 40337517, 2025). "We demonstrated that UTMB may promote the homing of mesenchymal stem cells to fibrotic liver by increasing the expression of CXCR4 on the surface of MSCs, and this study enriches the treatment of liver fibrosis and has broad prospects in stem cell therapy on liver fibrosis." (PMID 38402155, 2024). "Additionally, it is hypothesized that the CXCR4/ SDF-1 axis that participates in liver fibrosis, can at the same time stimulate the migration & homing of HPSCs to the injured liver." (PMID 37730560, 2023). "In contrast, aged mice exhibited hepatic fibrosis, with increased collagen deposition and upregulation of genes related to fibrosis (Acta2, MMP2, TGF-ß1, and Col1a2), cirrhosis (CXCR4, SOX9, DCN, and MFAP4), and cancer (Bcl2, CDKN2a, c-Myc, and Fn1)." (PMID 39851554, 2025). "The CXCL12/CXCR4/CXCR7 chemokine axis is well known to regulate cell migration and is involved in the regulation of liver fibrosis." (PMID 38360740, 2024). "Among these hub genes, some are cytokines and chemokines closely related to liver fibrosis (IFNG, CCL3, CCL4, CCL5, and CXCR4)." (PMID 35903097, 2022). "Our results are consistent with previous studies on liver fibrosis and expand them to AALD to suggest similarly complex effects of CXCR4 inhibition on the AALD fibrosis liver microenvironment." (PMID 35336043, 2022). "While the induction of the receptors CD74 and CXCR4 is comparable between the models, there is a marked up-regulation of chemokine receptor CXCR2 in MCD-treated mice compared to the CCl4-induced liver fibrosis model." (PMID 33525493, 2021). "Further, CXCL12 induces HSC proliferation and subsequent production of collagen I. In the current study, we evaluated AMD070, an orally bioavailable inhibitor of CXCL12/CXCR4 in alleviating BLM-induced pulmonary and CCl4-induced hepatic fibrosis in mice." (PMID 26998906, 2016). "Conversely, in hepatic fibrosis, resident hepatic stellate cells (HSC), the key cell type in progression of fibrosis, upregulate CXCR4 expression in response to activation." (PMID 26998906, 2016). "We hypothesized that the CXCR4 antagonizing polymer used in this DDS, can efficiently deliver therapeutic anti-miR155 to KC and inhibit CXCR4 on HSC in parallel and reverse liver fibrosis." (PMID 40313365, 2025). "Furthermore, we examined the relative mRNA expression levels of key markers related to hepatic fibrosis (Acta2, Cola2, TGF-β1, and MMP2), cirrhosis (CXCR4, SOX9, DCN, and MFAP4), and cancer (Bcl2, CDKN2a, c-Myc, and Fn1) across the experimental groups." (PMID 39851554, 2025). "Interestingly, we discovered that ALB not only inhibits inflammation to improve liver fibrosis by targeting the CXCL12/CXCR4 axis, but also synergizes with MET to inhibit the progression of liver fibrosis." (PMID 40371331, 2025). "HIV-1 alone did not induce liver fibrosis in hu-mice, even though previous reports showed that CXCR4-tropic HIV-1 induces the activation of HepSCs in vitro." (PMID 35639478, 2022). "In a mouse model of CCl4-induced liver fibrosis, the CXCL12/CXCR4 pathway is a critical chemotactic axis regulating the migration of MSCs from the bone marrow to the fibrotic liver, and recruited MSCs play different roles, including aggravating liver fibrosis and attenuating liver injury." (PMID 34386499, 2021).
liver fibrosis (continued). "The presence of CXCR4-using viruses in patients receiving a potent antiretroviral therapy does not influence HCV RNA concentration or liver fibrosis." (PMID 23226258, 2012). "We assessed the prevalence of CXCR4-using viruses in a population of HIV–HCV co-infected patients and investigated the influence of HIV-1 tropism on plasma concentration of HCV RNA and HCV-related liver fibrosis." (PMID 23226258, 2012). "The results revealed that effective suppression of the CXCL12/CXCR4 axis and Notch pathway through AMD3100-assisted siRNA therapy is promising for the inhibition of macrophage migration to inflammatory sites, thereby preventing hepatic fibrosis and alleviating MASLD." (PMID 40002899, 2025). "Recent studies have indicated that inhibiting the CXCL12/CXCR4 axis does not improve liver fibrosis and may even worsen it." (PMID 38360740, 2024). "Therefore, applying compound 18a in the in vivo lung and liver fibrosis models allowed us to evaluate the anti-fibrotic effect of pure ACKR3 agonism in the absence of CXCR4 antagonism, which has never been addressed before." (PMID 35562519, 2022). "In contrast, transplanted CXCR4-positive expanded endothelial progenitor cells (EPCs), induced by CXCL12 into the rat liver portal tracts, fibrous septa and hepatic sinusoids, effectively promote the remodeling of damaged tissues of liver fibrosis and suppress liver fibrogenesis." (PMID 34386499, 2021). "However, simply blocking profibrotic CXCL12/CXCR4 axis is not sufficient to ameliorate liver fibrosis in vivo." (PMID 34386499, 2021). "In addition to their role in liver fibrosis, it is argued that high levels of CCL2 can severely affect the course of HIV infection by up-regulating HIV-co-receptor CXCR4 on CD4+ T cells and polarization of helper T cells towards Th2 phenotype, a hallmark of progressive HIV disease." (PMID 25528160, 2014). "Though there is no consensus on the role of CXCR4 in AALD fibrosis, there are studies showing that the blockading of CXCR4 signaling suppresses HSC activation and proliferation, leading to a downregulation of collagen I and α-SMA expression in liver fibrosis." (PMID 35336043, 2022). "The selective profile of this small molecule (i.e., being a potent ACKR3-agonist without CXCR4 antagonism) allowed us to evaluate the role of pure ACKR3-agonism, thus ruling out the potential additional effect of CXCR4 antagonism, in mouse models of lung and liver fibrosis." (PMID 35562519, 2022).
lupus (34 papers, 2012 to 2026). "In addition to highlighting the unique interest of using soluble ligands, here CXCL12, as potentially valuable drug targets, the results underline the importance of the CXCL12/CXCR4 axis in lupus pathophysiology." (PMID 34744730, 2021). "The results underline the importance of the CXCL12/CXCR4 axis in lupus pathophysiology." (PMID 34744730, 2021). "In animal models, lupus-prone mice exhibit high CXCR4 expression in B cells, monocytes, neutrophils, and plasma cells, along with significantly elevated CXCL12 levels in the glomeruli and tubules." (PMID 41601976, 2026). "Specifically, ligand–receptor pairs such as Thy1-(Itgam+Itgb2), Mif-(Cd74+Cxcr4), Tgfb1-(Tgfbr1+Tgfbr2), and Pecam1-Pecam1 showed higher mean expression levels in lupus mice than in DHA-treated mice." (PMID 40728997, 2025). "This includes CXCR4+ extrafollicular helper T cells in murine lupus, as well as CXCR5− Tfh-like cells in lungs of mice with chronic Ag-driven inflammation, and T resident helper cells observed in lungs of mice with influenza." (PMID 40964009, 2025). "As a result of these findings, CXCL12/CXCR4 interactions play a crucial role in numerous physiological processes and are likely to significantly impact pathological conditions such as lupus." (PMID 39070795, 2024). "Studies in lupus-prone murine models demonstrated that CXCR4 was upregulated in B cells, monocytes, neutrophils, and plasma cells, driven by toll-like receptors (TLRs) and pro-inflammatory cytokines." (PMID 39070795, 2024). "Chemokines, particularly CXCR4 and CXCL12, are strongly associated with B-cell infiltration in the kidneys of lupus-prone MRL/lpr mice." (PMID 37872565, 2023). "Our study suggests that Nrf2 gene overexpression (Blood PCs 0.28%, Blood PC 0.92%; Kidney PCs 5.75%, Kidney PC 2.06%) regulates TLR4+CXCR4+ PCs and PC levels in the blood and kidneys of a mouse model of lupus, with concomitant amelioration of damaged tissue." (PMID 37872565, 2023). "Some other studies, however, showed that expression of CXCR4 remained unchanged or was decreased in all memory T cell subtypes from lupus patients compared to controls." (PMID 34744730, 2021). "Some studies pioneered this field to some extent and notably pointed out the importance of the CXCL12/CXCR4 pathway in systemic lupus erythematosus (SLE) physiopathology." (PMID 34744730, 2021). "Investigations performed by different groups demonstrated variable results regarding possible changes in the expression levels of CXCL12 and CXCR4 in lupus." (PMID 34744730, 2021). "Hyperexpression of CXCR4 on several peripheral blood leukocyte subsets was demonstrated in murine lupus models with active nephritis, namely (NZBxNZW)F1, B6.Sle1Yaa, BXSB, and MRL/lpr (Murphy Roths large/lymphoproliferation) mice." (PMID 34744730, 2021). "In an independent study including Mexican Mestizos patients with lupus, a significant defect in CXCR4 expression was detected at the surface of naive and antibody-secreting B cells, associated with an abnormal intracellular localization of the receptor." (PMID 34744730, 2021). "In the B6.Sle1Yaa model, the CXCR4 peptide inhibitor CTCE-9908 was shown to be very potent at reducing cellular and clinical lupus-linked failures." (PMID 34744730, 2021). "Patients with systemic lupus erythematosus (SLE) have a significant increase in cardiovascular (CV) risk although they display a preserved number of circulating angiogenic CD3+CD31+CXCR4+ T cells (Tang), a subpopulation of T cells which promotes repair of damaged endothelium." (PMID 33193356, 2020). "In several lupus models, CXCR4 expression is increased in B cells, plasma cells, T cells, neutrophils, and monocytes, which concurs with the increased CXCL12 expression in the kidney." (PMID 31507535, 2019).